STAT3 (signal transducer and activator of transcription 3)
Diseases named in the same sentence as STAT3 in open-access papers (continued):
Sharing a sentence is not in itself a finding about the gene and the disease.
lung carcinoma (continued). "In this regard, we first evaluated STAT3 activity in A549 and SW900 lung cancer cells, compared to normal cells (HFL-1), observing a significant increase in basal STAT3 signaling in cancer cells, accompanied by higher levels of survivin expression." (PMID 31412593, 2019). "In lung cancer cells, hypoxia-induced increase in miR-103a levels leads to the activation of AKT and signal transducer and activator of transcription 3 (STAT3) via inhibition of PTEN." (PMID 31086184, 2019). "Overall, our results elucidated a crucial role of LDOC1 in lung cancer and revealed how LDOC1 acts as a bridge between tobacco exposure and the IL-6/JAK2/STAT3 loop in this human malignancy." (PMID 30634502, 2019). "In the contrary, PI3k or Stat3 inhibition eliminated GJIC even in normal fibroblasts or epithelial cells, or certain lung cancer lines which have extensive GJIC." (PMID 30717267, 2019). "BBI608, a STAT3 inhibitor, reduced not only the viability of EGFR-positive lung cancer cell lines but also the expression of G9a and HER3." (PMID 31619200, 2019). "In this study, we investigated the inhibitory effects of a novel small-molecule inhibitor of STAT3, STX-0119, on the cell viability and survival of human lung cancer cells." (PMID 32257917, 2019). "The present study demonstrated that STAT3 promotes HER3 expression through the activation of G9a, which, in turn, represses HER3-targeted miR-145-5p expression in EGFR-positive lung cancers." (PMID 31619200, 2019). "Our data demonstrated that the knockdown‐mediated promotion of tumor metastasis is dependent on the STAT3 signaling pathway and that KLF3 expression is markedly related to lung cancer development in a clinical database." (PMID 31486564, 2019). "Curcumin exhibited its therapeutic efficiency in lung cancer treatment by means of the downregulation of NF-κB in human lung cancer cell lines A549 and also by acting on the JAK2/STAT3 signaling pathway, inhibiting JAK2 activity." (PMID 31590362, 2019). "In particular, antitumor activity of an ASO inhibitor of STAT3 (i.e., AZD9150) was observed in two phase 1 studies in patients with highly treatment‐refractory lymphomas and non‐small cell lung cancer." (PMID 31361391, 2019). "Different signaling pathways such as AKT/mTOR pathway, STAT1, and STAT3 pathway, ERK pathway played a critical role in the progression of lung cancer." (PMID 29788985, 2018). "Knockdown of TESC suppressed CSC-like properties as well as STAT3 activation through inhibition of insulin-like growth factor 1 receptor (IGF1R), a major signaling pathway of lung cancer stem cells." (PMID 30013043, 2018). "Considering both IL6 and aggressiveness of lung cancer cells up-regulation upon treatment with E2, meanwhile blocking IL6/Stat3 signal pathway reverse the effect." (PMID 29970138, 2018). "Importantly, the present results help elucidate the mechanism underlying PLOD3-mediated regulation of STAT3 function via direct interactions; PLOD3 may induce robust binding of STAT3 to its consensus-binding elements and upregulate target genes, thereby promoting lung cancer metastasis." (PMID 30442941, 2018). "PLOD3 and the STAT3 pathway were significantly correlated in the metastatic foci of lung cancer patients; PLOD3–STAT3 levels were highly correlated with a poor prognosis." (PMID 30442941, 2018). "Thus, these earlier reported findings on the link between STAT3 signaling, NF-κB activation, and K-ras mutant lung cancer pathogenesis are in close agreement with our present data showing increased lung tumor burdens in K-ras mutant-induced male mice specifically following epithelial Stat3 deletion." (PMID 30389925, 2018).
lung carcinoma (continued). "In a rescue assay, exogenous expression of STAT3 partially suppressed 6-OAP-induced apoptosis of the cells, suggesting that inhibition of STAT3 at least partially mediated the anti-lung cancer effect of 6-OAP." (PMID 27835873, 2017). "In the present study in lung cancer, LINC00152 knockdown leads to reduced several cell growth-related proteins such as STAT3, p38α, CREB1, STAT1, c-MYC and CCNE1." (PMID 28592840, 2017). "Further mechanistic studies demonstrated that CAFs enhanced the metastatic potential of lung cancer cells by secreting IL-6, subsequently activating of JAK2/STAT3 signaling pathway." (PMID 29100297, 2017). "The invasive abilities of lung cancer cells are regulated by different signaling pathways, among which PI3K/AKT and STAT3 pathways are frequently activated in cancer cells resulting in tumourigenesis and progression." (PMID 28903339, 2017). "We detected the phosphorylation of STAT3, ERK, AKT and FAK in lung cancer cells expressing either wild type BMX or BMXΔN and control cells followed by EGF stimulation." (PMID 28422715, 2017). "Our study showed that not only exogenous Stat3 and Hdac7 proteins expressed in 293T cells were co-immunoprecipitated reciprocally, but also endogenous STAT3 and HDAC7 proteins in human lung cancer cells and mouse lung tumors from control K-Ras mice." (PMID 29126425, 2017). "Signaling pathways regulated by TGF-β in lung cancer cells include Wnt/β-catenin, MAPK, and JAK/STAT3 signaling." (PMID 28819126, 2017). "It was also noted that EGFR mutant lung cancer cell lines selectively activate AKT and STAT3 signaling pathways, promoting cell survival." (PMID 28521301, 2017). "In the current study, we demonstrate, for the first time, that ING5 knockdown promotes invasion of lung cancer cells by inducing EMT via EGFR/PI3K/Akt and IL-6/STAT3 signaling pathways." (PMID 28903339, 2017). "To confirm that the effect of RIP4 on invasiveness of lung cancer cells is due to its inhibitory effect on STAT3, we developed M8 cells that can overexpress RIP4 and/or Stat3." (PMID 28574510, 2017). "Overexpression of ING5 in lung cancer A549 and H1299 cells and colorectal cancer HCT116 cells significantly reversed activation of both PI3K/Akt and STAT3 pathways." (PMID 28903339, 2017). "In order to correlate our findings with lung cancer prognosis in clinical settings, we analyzed the data from 1405 lung cancer patients and the gene expression of miR-218 host genes (SLIT2/SLIT3), IL-6, IL-6R, JAK3 and STAT3 in their tumor tissues." (PMID 28830450, 2017). "Blockade of JAK2/STAT3 and TGF-β signaling by specific inhibitors significantly inhibited cell proliferation in vitro and tumor growth in vivo of lung cancer cells." (PMID 28819126, 2017). "LSS-11, a novel triazolonaphthalimide-based topoisomerase inhibitor, overcomes paclitaxel-resistance in lung cancer cells via DR5/PARP1-mediated apoptosis and STAT3-mediated downregulation of MDR1 and MRP1." (PMID 29072615, 2017). "Inactivation of STAT3 by 6-OAP also resulted in transcription suppression of Skp2, enhancing the inhibitory effect of 6-OAP on Skp2 to suppress lung cancer." (PMID 27835873, 2017). "Our previous mechanistic characterization of the anti-cancer activity of NSC-743380 in lung cancer cells revealed that NSC-743380 induced robust ROS and suppressed STAT3 activation, both contributed to the anticancer activity of NSC-743380 and its analogues." (PMID 29254232, 2017). "Abnormalities in the IL-6/JAK/STAT3 pathway are also due to expression of a variety of oncogenes, such as Myc and VEGF, reportedly increased in lung cancer and other cancer types." (PMID 28830450, 2017). "The dimer formed by phosphorylated STAT3 (Y-705) goes into the nucleus, directly binds to the promoter region of BECN1 and represses its transcription in lung cancer cells." (PMID 28526807, 2017). "This notion is supported by the observation that paclitaxel activated STAT3 and upregulated MRP1 in lung cancer cells." (PMID 29072615, 2017).
lung carcinoma (continued). "Because the inhibition of JAK1/STAT3 signaling exhibits potent tumor-suppressive effects on lung cancer, it is important to study how IL10 induces JAK1/STAT3 signaling in cancer development." (PMID 26956044, 2016). "Signal transducer and activator of transcription 3 (STAT3) activation is commonly observed in multiple myeloma, chronic lymphocytic leukemia, gastric cancer, lung cancer, and laryngeal carcinoma." (PMID 26881027, 2016). "According to the experimental evidence that leptin, JAK/STAT3, and Notch are intimate partners in crime with regard to tumorigenesis, we hypothesize that targeting inactivation of these pathways by leptin knockdown may be a novel treatment approach for lung cancer." (PMID 27185268, 2016). "Homoharringtonine (HHT), another natural compound extracted from Cephalotaxus harringtonia, significantly inhibits the STAT3 activity by suppressing the IL-6/JAK1/STAT3 signaling pathway and induces the apoptosis of Gefiinib-resistant lung cancer cells." (PMID 26631279, 2015). "Resistance to EGFR inhibitors reportedly involves activation of signal transducer and activator of transcription 3 (STAT3) in glioma and lung cancer." (PMID 26542452, 2015). "Apart from transforming growth factor beta (TGF-β), IL-6 has been documented to be involved in lung cancer EMT via signal transducer and activator of transcription 3 (STAT3), Notch pathway." (PMID 26528698, 2015). "For example, persistent activation of STAT3 and STAT5 has been reported in breast cancer, lung cancer, glioma, liver cancer, pancreatic cancer, and nasopharyngeal carcinoma cases." (PMID 24662938, 2014). "Our data suggest that KIF5B-RET promotes the cell growth and tumorigenicity of non-small cell lung cancers through multilevel activation of STAT3 signaling, providing possible strategies for the treatment of KIF5B-RET positive lung cancers." (PMID 25047660, 2014). "Using RNAi-mediated inhibition of STAT3 expression, Yin and colleagues showed enhanced sensitization to radiotherapy in A549 and SK-MES-1 lung cancer cells." (PMID 25268165, 2014). "Accumulating evidence has demonstrated that aberrant expression and activity of STAT3 is implicated in both carcinogenesis and development of drug resistance in several cancer types, including NSCLC, suggesting that STAT3 may contribute to resistance to EGFR TKI treatment in lung cancer." (PMID 24280348, 2013). "PTX has also been shown to inhibit STAT3 phosphorylation in B16F10 melanoma and A549 lung carcinoma (our unpublished data)." (PMID 24199193, 2013). "Given that Stat3 signaling is usually activated in cancers, our findings suggest a potential mechanism for the down-regulation of PTPN13 in lung carcinoma." (PMID 24191246, 2013). "In conclusion, our results suggest that interruption of both STAT3-survivin and ERK–BIM signalling is required for the induction of apoptosis in lung cancer cells harbouring EML4–ALK." (PMID 22240786, 2012). "Collectively, these data suggested that simultaneous interruption of STAT3-survivin and ERK–BIM signalling pathways is required for the induction of apoptosis in EML4–ALK-positive lung cancer cells." (PMID 22240786, 2012). "Although two HDACis, LBH589 and AR-42, have been shown to reduce STAT3 levels in human lung cancer cells and malignant mast cell disease, respectively, the effects of SNDX-275 on STAT3 activation and/or expression in MM cells remain unknow." (PMID 21679466, 2011). "SU6656 has been shown to decrease activation of STAT3 and subsequent downstream targets in NIH3T3 cells resulting in cell cycle arrest and apoptosis in human lung cancer cells." (PMID 19284568, 2009).
lung carcinoma (continued). "To explore the possibility of a double-stranded decoy oligodeoxynucleotide (ODN) targeted blocking STAT3 over-activated tumor cells, we, here, evaluate the efficacy of STAT3 decoy ODN on human lung cancer cells in vitro and in vivo." (PMID 17683579, 2007). "We observed a positive correlation between STAT3 and CD47 expression in lung cancer." (PMID 41438583, 2026). "Emerging evidence indicates that activation of STAT3 is one of the contributors to EGFR-TKI resistance, and targeted inhibition of STAT3 signaling has shown potential to circumvent therapeutic resistance both in lung cancer and other malignancies." (PMID 41539998, 2026). "Moreover, our study highlights the clinical relevance of these findings, demonstrating the increased expression of SHH, p‐STAT3, and GLI1 proteins in postosimertinib‐resistant lung cancer tissues, along with decreased DUSP13B expression." (PMID 39721017, 2025). "Additionally, in lung cancer (A549) cells, UA inhibits the JAK2/STAT3 pathway, reducing cancer stem cell marker expression and tumor stem cell populations, which sensitizes these cells to cisplatin [1050]." (PMID 40490812, 2025). "It has been reported that Gal-3 enhanced the protein expression of immune checkpoint ligand PD-L1 in lung cancer cells in vitro by increasing STAT3 phosphorylation, while a Gal-3 inhibitor (GB1107) decreased both PD-L1 expression and STAT3 phosphorylation in these cells." (PMID 40566589, 2025). "Pro-inflammatory cytokines relevant to pulmonary oncology intersect with checkpoint pathways: IL-6 trans-activates JAK/STAT3 in lung cancer and can upregulate PD-L1, while EGFR signaling on tumor cells converges on the IL-6–STAT3 axis to enhance PD-L1 expression." (PMID 41440526, 2025). "The reviewed studies often do not differentiate the tumor heterogeneity sufficiently, which may influence the generalizability of STAT3‐targeted CUR and RES therapies across all lung cancer types." (PMID 40860906, 2025). "Given the challenges in treating ICI-resistant lung cancer, this study investigates the synergistic effects of SH003 and DTX in anti-PD1-refractory cancer models by simultaneously targeting STAT3-mediated signaling and enhancing immune cell function in the TME." (PMID 40347254, 2025). "While the regulation of STAT3 phosphorylation is yet to be understood, we demonstrated that it is dependent on the JAK activation but not on EGFR; the former is often overactivated in lung cancer cells." (PMID 39985075, 2025). "Additionally, exosomes extracted from TAMs promote TKI resistance in lung cancer cells through AKT, ERK1/2, and STAT3 signaling pathway reactivation." (PMID 40002883, 2025). "In addition, the signal transducer and activator of transcription 3 (STAT3) has been found to directly bind to GPR81 promoter and activate GPR81 expression in lung cancer cells." (PMID 38982366, 2024). "Moreover, clinical analyses revealed a positive correlation between STAT3 and EGFR mRNA levels in lung cancer." (PMID 39967270, 2024). "The addition of the SPHK2 inhibitor, ABC294640, to the RPTOR-overexpressed PC9 cells significantly inhibited the RPTOR-induced activation of the SPHK2/S1P/STAT3 signaling pathway and restrained the RPTOR overexpression-enhanced proliferation, migration and invasion of lung cancer cell lines." (PMID 38163890, 2024). "Notably, our findings reaffirm the relevance of lung cancer genes, such as CTNNB1, STAT3, HIF1A, HSP90AA1, and ERBB2, integral to various cellular processes and pivotal in cancer genesis and advancement." (PMID 39113883, 2024). "Furthermore, cucurbitacin E and B inhibited the activation of both STAT3 and JAK2 but mildly activated apoptosis and suppressed tumor growth in lung cancer." (PMID 38397437, 2024).
lung carcinoma (continued). "Specifically, the investigation revealed a connection between the phytochemical constituents and the genes CTNNB1, STAT3, HIF1A, HSP90AA1, and ERBB2, which have established links to lung cancer and play essential roles in the critical cellular pathways involved in disease progression." (PMID 39113883, 2024). "Mechanistically, IGFBP2 can activate STAT3 to enhance the transcriptional activity of CXCL1, thereby increasing the intracellular expression level of CXCL1, which contributes to the survival of lung cancer cells in the gefitinib environment." (PMID 38918360, 2024). "Moreover, we performed Kaplan-Meier analysis to assess the prognostic value of STAT3 and ACC1 in lung cancer patients." (PMID 38495496, 2024). "Furthermore, analysis of the TCGA database revealed a positive correlation between STAT3 expression and ACC1 in lung cancer patients." (PMID 38495496, 2024). "In summary, these findings suggest that STAT3 may modulate ACC1 expression to regulate the proliferation and migration of lung cancer cells." (PMID 38495496, 2024). "Promoted metastasis in lung cancer via NG2+ perivascular cells and STAT3 signaling (in vivo)." (PMID 38745756, 2024). "Similarly, activation of the JAK2/STAT3 pathway in TAMs promoted lung cancer metastasis, which was attenuated by knockdown or the use of JAK2/STAT3 inhibitors." (PMID 38424624, 2024). "Additionally, DHA efficiently inhibited the phosphorylation of STAT3 and the inactivation of STAT3, leading to the downregulation of Mcl-1 and survivin, which improved the chemosensitivity of ABT-263 in lung cancer cells." (PMID 38397437, 2024). "For example, serum CSF2 level has been demonstrated to be increased in patients with lung cancer, and CSF2‐dependent activation of the JAK2/signal transducer and activator of transcription 3 (STAT3) pathway is important in tumor angiogenesis and vascularization." (PMID 39036343, 2024). "However, exo-miRNAs promote proangiogenic factor in melanoma and lung cancer via miR-155-5p and by miR-210 via the JAK2/STAT3 signaling pathway, respectively." (PMID 39075612, 2024). "STAT1's function is similar to STAT3, affecting SLC7A11 expression in lung cancer." (PMID 39104501, 2024). "AKT1, EGFR, and STAT3 were enriched in the non-small cell lung cancer (NSCLC) pathway according to Kyoto Encyclopedia of Genes and Genomes analysis, indicating a significant connection to lung cancer development." (PMID 38731403, 2024). "STAT3 may be involved in different USP21-mediated cancer progression pathways, such as USP21-YY1-SNHG16 axis in non–small cell lung cancer." (PMID 39305962, 2024). "In addition, there is tight crosstalk between STAT3 and TGF-β signaling in various cancers, including gastrointestinal cancer, lung cancer, and hepatocellular carcinoma." (PMID 38136312, 2023). "By reducing STAT3 phosphorylation, CYTL1 prevents lung cancer tumor spread." (PMID 37745303, 2023). "In lung cancer cell lines and PDX models, aldo-keto reductase family 1 member B1 (AKR1B1) promoted glutathione de novo synthesis by activating signal transducer and activator of transcription 3 (STAT3), leading to ROS scavenging and ultimately to EGFR-TKI drug resistance." (PMID 36911198, 2023). "In addition, we clarify that Q11 can inhibit the activation of the IL‐6/STAT3 pathway and the MAPK/ERK pathway, suggesting that Q11 regulates specific signaling pathways critical for inflammatory responses in lung cancer." (PMID 37875398, 2023). "Taken together, we in this study conclude that lack of SIRPα attenuated lung cancer growth in mice by reducing SHP‐1/STAT3/p38 MAPK signalling, subsequently suppressing IL‐6 expression, meanwhile improving M1 and N1 subtypes and their phagocytosis activity." (PMID 36419386, 2023).